GPATCH8 (G-patch domain containing 8)
Synonyms: GPATC8; KIAA0553
Tractability: PROTAC: UniProt records ubiquitination sites on it; ubiquitination databases record sites on it; its protein half-life has been measured.
Gene: Protein-coding gene on chromosome 17 (44,395,281 to 44,503,595, reverse strand). Ensembl gene ENSG00000186566.
Subcellular location (Human Protein Atlas): Nuclear speckles; Mitochondria
Gene Ontology:
Molecular function: protein binding; RNA binding; mRNA binding; nucleic acid binding
Cellular component: nucleus
Genetic constraint (gnomAD): Loss-of-function variants: 14 observed, 86.4 expected, observed/expected ratio (o/e) 0.16, 90% interval 0.11 to 0.25. The upper end of that interval is the gene's LOEUF score, 0.25, which puts it in group 1 of 6, group 1 being the genes least tolerant of losing a copy. Missense variants: 1,533 observed, 1,701.3 expected, observed/expected ratio (o/e) 0.9, 90% interval 0.86 to 0.94. Synonymous variants: 595 observed, 635.25 expected, observed/expected ratio (o/e) 0.94, 90% interval 0.88 to 1.
Homologues: Orthologues: chimpanzee GPATCH8 (99% identical), macaque GPATCH8 (99% identical), dog GPATCH8 (95% identical), pig GPATCH8 (94% identical), rabbit GPATCH8 (92% identical), mouse Gpatch8 (90% identical), rat Gpatch8 (89% identical), guinea pig GPATCH8 (76% identical), tropical clawed frog gpatch8 (55% identical), zebrafish gpatch8 (49% identical). Paralogues in human: ZNF804B (25% identical), ZNF804A (22% identical).
Diseases named in the same sentence as GPATCH8 in open-access papers:
GPATCH8 is named in the same sentence as 7 diseases in open-access papers, as found by Europe PMC text mining. Sharing a sentence is not in itself a finding about the gene and the disease. The quoted sentences say what the papers report.
schizophrenia (2 papers, 2019 to 2023). A major psychotic disorder characterized by abnormalities in the perception or expression of reality. "An additional link to schizophrenia is a frameshift variant in the GPATCH8 gene in exon 9 of transcript GPATCH8-201, an ortholog of ZNF804A, which has been shown to impact various mental illnesses via pre-mRNA processing." (PMID 36449109, 2023). "We show that ZNF804A is a nuclear protein that interacts with neuronal RNA splicing factors and RNA-binding proteins including RBFOX1, which is also associated with schizophrenia, CELF3/4, components of the ubiquitin-proteasome system and the ZNF804A paralog, GPATCH8." (PMID 30597088, 2019).
tumor (1 paper, 2024). "However, other genes with similar tumor suppressive function in our screen, such as Ambra1, Gpatch8, and Spred1, may be less appreciated as tumor suppressors." (PMID 38302473, 2024).
GPATCH8 also shares sentences with these, for which no sentence is quoted: breast carcinoma (1 paper); cancer (1); infection (1); mental illnesses (1); myopia (1).